EZH2 (enhancer of zeste 2 polycomb repressive complex 2 subunit)
Diseases named in the same sentence as EZH2 in open-access papers (continued):
Sharing a sentence is not in itself a finding about the gene and the disease.
leukemia (continued). "We next generated primary MLL-AF9 or AML1-ETO9a leukemias in recipient mice using transformation of Ezh2−/− HSPCs and compared survival and phenotype to Ezh2+/+ leukemias generated by the same oncogenes." (PMID 30890554, 2019). "The RDS 3434 inhibitor has been shown to be specifically active against EZH2 in human leukemia cells, where it induced heavy cell death in a dose-dependent manner." (PMID 31619182, 2019). "Some data about the involvement of EZH2 have been collected using a murine model of NRASQ61K-driven leukemia that shows the phenotypic and transcriptional aspects of ETP-ALL." (PMID 30510924, 2018). "Although EZH2 is an attractive target to harness donor allo-reactive T cells in the post-transplant setting to modulate GvHD and the anti-leukemia effect, our results suggest that more selective and effective ways to inhibit EZH2 in human T cells are required." (PMID 30452487, 2018). "In particular, homozygous inactivation of EZH2 cooperates with oncogenic NRASQ61K to favor leukemia development." (PMID 30510924, 2018). "A stabilized alpha-helix mimetic of the EZH2 peptide has been shown to selectively inhibit H3K27 trimethylation of PRC2 in vitro and suppresses the growth of MLL-AF9 leukemia cells via disrupting the EZH2/EED interaction." (PMID 28072869, 2017). "We used this approach to identify novel resistance alleles of two lysine methyltransferases, DOT1L and EZH2, which are each essential for the growth of MLL-fusion leukemia cells." (PMID 28231254, 2017). "Studies also reported prolonged OS and reduced tumour burden in MLL-AF9 leukaemia model by targeting of a H3K27 methyltransferase EZH2." (PMID 27593928, 2017). "In summary, MYCN/EZH2 axis is critical for cell growth, anti-apoptosis, cycle progression, anti-senescence and self-renewal of leukemia cells through repression of p21 expression." (PMID 29022893, 2017). "It has been shown that Ezh2 is required for proper B and T cell development suggesting that lower Ezh2 expression would affect differentiation of both lymphocyte subpopulations, similar to the observed effect in leukemia patients." (PMID 28078190, 2017). "Overexpression of EZH2 enhanced the malignant characteristics of leukemia cells, whereas downregulation of EZH2 diminished them." (PMID 29022893, 2017). "EZH2 was recently identified as promoting leukemia stem cell (LSC) tumorigenesis by suppressing cell differentiation and maintaining stem cell properties." (PMID 28415635, 2017). "Taken together, our results suggest that CD82 regulates the expression of EZH2 in leukemia cells via p38 MAPK signaling, resulting in both H3K27me3 and methylation in the PTEN promoter region, thereby resulting in repression of PTEN transcription." (PMID 25955299, 2015). "The present study found that CD82 positively regulates both the expression and phosphorylation of EZH2 in leukemia cells via inactivation of p38 MAPK signaling." (PMID 25955299, 2015). "A chromatin immunoprecipitation assay was performed to examine the effect of CD82 expression on the amount of EZH2 bound to the promoter regions of tumor suppressor genes in leukemia cells." (PMID 25955299, 2015). "We identified 104,370 genomic regions that are enriched for both EZH2 and H3K27me3 in the leukemia cell line (K562) and 53,360 regions in the lymphoblastoid cell line (GM12878)." (PMID 26043758, 2015). "Real-time RT-PCR and western blot analysis were performed to examine the effect of CD82 knockdown on the expression of the polycomb group member, enhancer of zeste homolog 2 (EZH2), in leukemia cells." (PMID 25955299, 2015). "To focus on EZH2-mediated coding-gene silencing that is specific to leukemia, we compared the candidates in leukemia with lymphoblastoids." (PMID 26043758, 2015).
leukemia (continued). "EZH2 occupancy and presence of H3K27me3 at promoters directly silences the transcription of targeted genes, which has been observed in leukemia and other tumors." (PMID 26043758, 2015). "Samples with the highest z-score values for KDM5A module and with the lowest z-score values for EZH2 module were found in leukemia samples of cluster 1, which was consistent with high expression of these modules in normal blood cell types." (PMID 21886846, 2011). "To examine whether similar findings in our mouse models can also be translated to human leukemia, we examined the TE expression profile of samples from patients with MDS carrying ASXL1/EZH2 mutations." (PMID 40561338, 2025). "In leukemia, such as MDS/AML, chromatin dysregulation plays a critical role through mutations in key DNA and histone modifiers, for example TET2, DNMT3A, ASXL1, and EZH2, which are frequently mutated in MDS/AML." (PMID 40562788, 2025). "EZH2 activates STAT3 signaling via STAT3 methylation in leukemia cells." (PMID 39730061, 2024). "Our focused studies on EZH2 and NRAS mutations provide an opportunity to dissect how distinct oncogenic pathways converge at the single-cell and single-gene levels to cause aberrant gene expression and leukemia progression." (PMID 34732703, 2021). "These in vivo data suggested that EZH2 inhibition by chidamide or shEZH2 decreased leukemia growth and increased the antileukemia effect of adriamycin through suppression of Smo/Gli-1 pathway in the leukemia-bearing mouse models." (PMID 33743723, 2021). "From these data we conclude that the presence of an MLL-FP or EZH2/H3K27me3 at the PROM1 promoter may determine whether it is expressed in leukemia cells." (PMID 32242051, 2021). "Similarly, in EZH2 inactivated leukemia stem cells (LSC), the combined effect of the loss of EZH2 and NRAS enhance BCAT1-mediated BCAA metabolism and upregulated the expression of genes involved in TCA (e.g., IDH)." (PMID 32448308, 2020). "The Co‐IP results showed significant binding of E2F4 and EZH2 in leukaemia cells and AML patients." (PMID 31943751, 2020). "Patients with EZH2 mutation showed shorter overall survival (OS) and leukaemia‐free survival (LFS) than patients without EHZ2 mutation after receiving autologous or allogeneic haematopoietic stem cell transplantation (HSCT)." (PMID 31794134, 2020). "Using a candidate gene approach, five mutated genes including ASXL1, SRSF2, EZH2, IDH1, and IDH2, which are reported to occur in 25–30% of all PMF patients, were associated with shorter OS and leukemia-free survival (LFS), defining a high-molecular risk (HMR) category." (PMID 31013941, 2019). "We next interrogated the role of EZH2 in the preleukemic state and leukemia induction." (PMID 30890554, 2019). "To further explain the contradictory and opposite effects of Ezh2 loss during AML induction and maintenance, we compared genes de-repressed in established MLL-AF9 leukemias following pharmacological inhibition of Ezh2 (62 genes) to genes derepressed during the induction of Ezh2−/− MLL-AF9 leukemias." (PMID 30890554, 2019). "Moreover, prior studies have demonstrated that MLL-fusion leukemia cells are addicted to EZH2 enzymatic activity, and hence RN2c cell line is a suitable model for identifying resistance alleles." (PMID 28231254, 2017). "Furthermore, we extended our method to identify an EZH2 mutant that rendered leukemia cells resistant to an EZH2 inhibitor, EPZ-6438." (PMID 28231254, 2017). "We observed the loss of EZH2 and H3K27me3 enrichment on the SEMA3A promoter in leukemia and hypothesized that this loss rescues SEMA3A expression and facilitates leukemogenesis after chemo- or radiotherapy." (PMID 26043758, 2015). "Moreover, the p38 inhibitor, SB203580, induced EZH2 expression in CD82-downregulated leukemia cells, suggesting that p38 directly downregulated the expression of EZH2." (PMID 25955299, 2015). "Notably, this study showed that EZH2 inhibitor (DZNep) increased the levels of MMP9 in leukemia cells." (PMID 25955299, 2015).
leukemia (continued). "To determine whether CD82 expression in leukemia cells affects the amount of PTEN promoter-bound EZH2 or the trimethylation status of H3K27 in this region, we performed ChIP assays using anti-EZH2 or-H3K27me3 antibodies in EOL-1R and MOLM13 cells." (PMID 25955299, 2015). "Furthermore, inhibiting EZH2 in vivo could not only reduce the frequency of leukemia-initiating cells (LICs) but also improve the survival of mice with MLL-AML." (PMID 39655332, 2024). "In addition, our work further validates EZH2 as a therapeutic target in MLL-rearranged leukemias and, from the use of another mouse model and a number of different AML patient samples, extends this therapeutic potential more generally across other AML genotypes." (PMID 30890554, 2019). "Moreover, neither expression of Plag1 nor Lin28b was significantly altered following GSK343 treatment of MLL-AF9 tumors, reinforcing the concept of disparity between transcriptional programs repressed by Ezh2 that are responsible for early tumor suppression and later maintenance of these leukemias." (PMID 30890554, 2019). "Interestingly, the NFkB family of proteins RelA as well as c-Rel were reported to enhance luciferase activity in an EZH2 reporter system, and c-Rel regulated the induction of EZH2 gene expression in activated primary murine lymphocytes and human leukemia cell lines." (PMID 29619032, 2018). "Interestingly, Ezh2 inactivation has been also observed in leukemia and Klf4 may function as a tumor suppressor gene in leukemia." (PMID 28078190, 2017). "We next examined whether CD82-induced EZH2 repressed the levels of MMP9 in leukemia cells." (PMID 25955299, 2015). "They further demonstrated that EZH2 and CMYC directly interact through EZH2’s transactivation domain (TAD) and that this interaction is essential for malignant growth of leukemia cells." (PMID 37664059, 2023). "Separately, EZH2 inhibitors combined with glucocorticoids or combination chemotherapy were reported as a promising treatment strategy for relapsed ALL with NSD2 mutations, providing further evidence that manipulation of PRC2 function might be therapeutically beneficial in some leukaemia subtypes." (PMID 36980579, 2023). "In summary, the combinatorial blockade of the EZH2 and BCL-2 shows a great synergistic anti-leukemia effect through upregulated PIK3IP1 and downregulated c-KIT." (PMID 36232694, 2022). "HDAC inhibitors decrease the expression of EZH2 and DNMT1 and increase hypomethylating agent-mediated apoptosis in human leukemia cells." (PMID 33743723, 2021). "For example, UNC1999 and SAH-EZH2 peptide (binds EED, resulting in dissociation of EZH1–EED and EZH2–EED complexes) showed activity against MLL leukemia." (PMID 34298959, 2021). "The role of PRC2 in leukemia has been studied, and in particular, the catalytic PRC2 core component EZH2 has been reported to be overexpressed in CML." (PMID 33996816, 2021). "Our previous studies showed that EZH2 overexpression and activation of Smo/Gli-1 pathway were related to the poor prognosis in AML patients, and Smo inhibitor effectively decreased leukemia growth and increased chemosensitivity." (PMID 33743723, 2021). "For instance, in CD133− leukemia cell lines such as THP1 and RCH-ACV, the promoter of PROM1 is bound by EZH2 (the enzymatic component of PRC2) and marked with H3K27me3, suggesting that the gene is polycomb-repressed." (PMID 32242051, 2021). "Although barely detectable in healthy donors, EZH2 was upregulated in both AML1-ETO-positive and AML1-ETO-negative leukemia cells, suggesting an AML1-ETO-independent mechanism." (PMID 31699991, 2019). "We were able to reproduce previous data that deletion of Ezh2 significantly disrupted the progression and prolonged survival of secondary MLL-AF9 leukemias." (PMID 30890554, 2019).
leukemia (continued). "We used two lncRNA constructs, HOTAIR440, a segment of HOTAIR that contains the region involved in binding to EZH2, MEG3, a lncRNA involved in leukemias and a 50 nt long RNA with random nucleotide sequence." (PMID 30400675, 2018). "To define the role of EZH2 in leukemia cells, we constructed HEL with stable overexpression and knockdown of EZH2 using the lentivirus-mediated transfection system." (PMID 29022893, 2017). "Recent studies have shown that EZH2 has a critical function in maintaining CSC properties and promoting CSC metastasis in various solid tumors as well as in leukemia." (PMID 28415635, 2017). "EZH2 knockdown increased tumor growth capacity and reduced H3K27me3 levels in both MDS-derived leukemia cells and in a xenograft model." (PMID 26812882, 2016). "Indeed, our results confirm that antibody-mediated inhibition of CD82 in leukemia cells interferes with DNA hypermethylation of the PTEN promoter region, and is associated with a decrease in both the level of H3K27me3 and the amount of EZH2 bound to the promoter." (PMID 25955299, 2015). "Etv6 and Runx1 are known leukemic regulators, and Suz12 and Ezh2 are core members of the Polycomb repressive complex 2 (PRC2), whose activities have been shown to be essential for MLL-AF9 driven leukemia." (PMID 25517911, 2014). "EZH2 inactivation leads to BCAT1 overactivation, enhancing BCAA metabolism and mTOR signaling, which together drive the transformation of myeloproliferative neoplasms into leukemia." (PMID 40438606, 2025). "Interestingly, MS177, a recently developed EZH2‐specific PROTAC degrader by other groups,[13b] achieved effective depletion of both EZH2 and interacting partners MYC in leukemia." (PMID 39823459, 2025). "Yet, we found that EZH2 was capable of generating leukemia in mice even in the absence of IDH1 or NRAS." (PMID 40362463, 2025). "Additionally, in an in vivo mouse model of AML1-ETO9a secondary leukemia treated with EPZ-6438 EZH2 inhibition, survival was prolonged with EZH2 inhibition compared to control." (PMID 39200232, 2024). "EED directly interacts with EZH2, therefore Orkin and colleagues developed peptides that selectively disrupt the EED/EZH2 interaction, thereby reducing EZH2 protein levels as well as H3K27me3 in MLL-AF9-mediated leukemia." (PMID 36105358, 2022). "For instance, EZH2, the catalytic subunit of PRC2, is overexpressed in CML leukemia-initiating cells (LICs), and its depletion in LICs results in decreased capacity to form secondary leukemia upon transplantation in a murine model." (PMID 36009388, 2022). "Indeed, a stage-specific and opposite function for EZH2 at the early and late stages of the disease was suggested; EZH2 acted as a tumor suppressor at the stage of AML induction, while it exerted an oncogenic function during leukemia maintenance." (PMID 34012921, 2021). "Moreover, and in keeping with our in vitro findings, we extended this oncogenic role for Ezh2, further demonstrating similar effects in AML1-ETO9a leukemias in vivo (respectively)." (PMID 30890554, 2019). "Critically, our detailed analysis demonstrates that Ezh2 functions only as a tumor suppressor during leukemia induction and that its catalytic inhibition does not up-regulate HOX genes during AML maintenance." (PMID 30890554, 2019). "EZH2 may therefore act as a tumor suppressor in MDS but as an oncogene in solid cancers and leukemia." (PMID 26812882, 2016). "Only around 10% of the identified ~17,400 EZH2 repressed coding-gene candidates are disease-specific, resulting in 1624 genes specific to lymphoblastoid but not leukemia." (PMID 26043758, 2015). "We previously found that long-term exposure of leukemia cells to imatinib induces expression of DNA methyltransferase 3A (DNMT3A) and EZH2, which then interact with one another and suppress the expression of phosphatase and tensin homolog deleted on chromosome ten (PTEN) in leukemia cells." (PMID 25955299, 2015).
leukemia (continued). "In addition, enriched EZH2 at the p16 transcription-start-site maintains H3K27 methylation status and suppresses the expression of p16 in mixed lineage leukemia fusion leukemia." (PMID 25955299, 2015). "An in vitro murine model demonstrated that there may be therapeutic utility in EZH2 inhibition (via GSK343 which is an S-adenosyl methionine-competitive inhibitor) in AML; EZH2 inhibition tested on primary human leukemia cells also demonstrated growth inhibition." (PMID 39200232, 2024). "In this context, inhibiting EZH2 in cell lines, primary cells and xenograft mouse models to de-condense the H3K27me3-marked chromatin of AML cells was shown to improve accessibility to chromatin and suppress leukemia through chemotherapy-induced DNA damage as well as apoptosis." (PMID 39655332, 2024). "Interestingly, leukemia, gastric tumor, and brain tumor cells withaltered levels of EZH2 did not respond to EZH2 inhibition by BR-001.Resistance to EZH2 inhibition was formerly linked to increased MLL1expression level and H3K27ac upregulation." (PMID 34351144, 2021). "RDS 3434 has been shown to be specifically active only against EZH2, and to be a selective EZH2 inhibitor in human leukemia cells where it induced heavy cell death in a dose-dependent manner, coupled with a reduction of H3K27me3 levels, without affecting EZH2 protein level." (PMID 31619182, 2019). "While mice with combined Ezh2 and Runx1 loss of function mutations targeted to early lymphoid progenitors (DKO mice) failed to develop leukemia and showed dramatically reduced thymus cellularity, the numbers of ETPs in the thymus were selectively and markedly expanded." (PMID 30652110, 2018). "However, in the leukemia cell line, a peak with both EZH2 and H3K27me3 enrichment has not been observed in the human genomic region within 150kbp distance to SEMA3A, suggesting a leukemia-specific loss of EZH2-silencing on SEMA3A." (PMID 26043758, 2015). "We then examined whether CD82 inactivates p38 in leukemia cells, and found that forced expression of CD82 in EOL-1 cells results in a 5-fold decrease in the level of p-p38 and increases in both phosphorylation at the threonine residues and total EZH2." (PMID 25955299, 2015). "Jin and Wang laboratories recently reported that the PROTAC MS177 achieved effective depletion of EZH2 in the context of both its canonical and non-canonical activities in MLL leukemias." (PMID 36105358, 2022).